BECN1 (beclin 1)
Diseases named in the same sentence as BECN1 in open-access papers (continued):
Sharing a sentence is not in itself a finding about the gene and the disease.
hepatocellular carcinoma (continued). "MiR-30a inhibits autophagy in chronic myeloid leukemia and hepatocellular carcinoma (HCC) cells by selectively blocking BECN1 and ATG5, which are needed for autophagy nucleation and elongation stages respectively." (PMID 38799506, 2024). "SIRT6 deacetylates Beclin-1 in hepatocellular carcinoma (HCC) cells and stimulates the autophagic degradation of E-cadherin, which in turn promotes epithelial-mesenchymal transition (EMT) in HCC cells and ultimately increases metastasis in liver cancer." (PMID 35915188, 2022). "Besides that, hypoxia-induced autophagy may also protect hepatocellular carcinoma cells from apoptosis during nutrient deprivation via Beclin-1 dependent pathway." (PMID 33743781, 2021). "The inhibition of Beclin-1 induces the reduction of autophagic activity in hepatocellular carcinoma (HCC), with a tendency to initiate the voluntary formation of malignant lesions in Beclin-1 heterozygous disruption mouse models." (PMID 33375363, 2020). "The aim of this study was to investigate BCL2L10 and BECN1 expression and their effect on autophagy in hepatocellular carcinoma (HCC)." (PMID 30696802, 2019). "Autophagy induction by SA was previously reported against hepatoma as SA increases LC3 and Beclin-1 levels." (PMID 40426893, 2025). "Silencing CISD2 reduced the cell proliferation of resistant hepatocellular carcinoma (HCC) cells by increasing ferroptosis, while inhibiting both CISD2 and BECN1 decreased ferroptosis in HCC cells." (PMID 39605902, 2024). "Bortezomib has been shown to increase the expression of Beclin-1, LC3-I, and LC3-II in hepatocellular carcinoma." (PMID 40034935, 2024). "In hepatocellular carcinoma, sorafenib and its derivative SC-59 both trigger autophagy through SHP-1-STAT3-Mcl-1-Beclin 1 pathway, with SC-59 showing greater efficacy in decreasing cancer cell viability and tumor growth." (PMID 39650649, 2024). "Another study reported that high levels of miR-101-3p suppressed autophagy in hepatocellular carcinoma cells by reducing LC3-II and Beclin-1 expression and increasing p62 expression." (PMID 35170378, 2022). "Luteolin treatment reportedly increased the number of intracellular autophagosomes, as indicated by an increased expression of Beclin 1, and conversion of LC3B-I to LC3B-II in hepatocellular carcinoma SMMC-7721 cells." (PMID 36482329, 2022). "Our results are in agreement with previous studies showing that TGF-β induces the expression of the autophagy-related genes BECN1, ATG5, and ATG7 through the SMAD signaling pathway in hepatocellular cancer cells, leading to the activation of autophagy." (PMID 34681055, 2021). "In HepG2 and MHCC97-L hepatic carcinoma cells, BBR induces autophagic cell death by the activation of Beclin-1 (BECN-1) and the inhibition of m-TOR signaling through the downregulation of Akt activity and the upregulation of P38 MAPK signaling." (PMID 32855766, 2020). "Combined with EGCG, doxorubicin played a concentration-dependent inhibitory role in autophagy signaling through increased Beclin-1 and Atg5 expression to inhibit autophagy and suppressed LC3 expression in hepatoma Hep3B cells." (PMID 32121322, 2020). "Beclin-1 expression was related to HBV infection status and the grade of hepatocellular carcinoma (HCC)." (PMID 33425768, 2020). "In a hepatocellular carcinoma (HCC) lung metastasis model, the inhibition of autophagy (via the lentivirus-mediated silencing of BECN1 and ATG5) markedly decreased the pulmonary metastasis of HCC cells." (PMID 25743109, 2015). "In the present study, we investigated the significance and relationship between Beclin-1 expression and cell proliferation, apoptosis, microvessel density (MVD) and clinical pathological changes or prognosis in human hepatocellular carcinoma (HCC)." (PMID 24885292, 2014).
hepatocellular carcinoma (continued). "The previous studies demonstrated that OA induced autophagy in colon cancer cells by regulating the p38/FOXO3a/Sirt6 pathway, and in hepatoma cells through the Akt/mTOR pathway, reflected in the decreased p62 expression and increased LC3-II and Beclin-1 expression." (PMID 40969279, 2025). "Furthermore, decreased expression of autophagy-related genes such as ATG5, ATG7, and Beclin-1 has been observed in hepatocellular carcinoma (HCC) cells, and our laboratory has confirmed that autophagy deficiency due to ATG5 knockout can induce malignant cellular transformation." (PMID 39519774, 2024). "Furthermore, SIRT6 enhances the EMT process in hepatocellular cancer (HCC), promoting E-cadherin autophagic degradation in a Beclin-1 dependent manner." (PMID 35745656, 2022). "Metastatic hepatocellular carcinoma cells with suppressed BECN1 expression failed to survive in the metastatic niche." (PMID 31272261, 2019). "Reportedly, the autophagy related gene Beclin 1 (BECN1), which plays an important role in the formation of phagophore and tumor suppression, is found to deplete in the human ovarian, breast, prostate cancers, as well as hepatocellular carcinoma and squamous-cell carcinomas." (PMID 36482329, 2022). "Some flavonoids, like quercetin, epigallocatechin gallate (EGCG), and apigenin, showed antiproliferative effects by upregulating the expression of beclin-1, LC3-II, and forms of Atg in cells of hepatocellular carcinoma (HCC)." (PMID 33114725, 2020). "In relation to autophagy, CAV1 appears to have an inhibitory role in hepatocellular carcinoma (HCC) since autophagy markers such as ATG5, Beclin-1, and LC3II were upregulated in HCCLM3-shCAV1 cells compared to mock cells." (PMID 31362353, 2019). "For example, in hepatocellular carcinoma (HCC), YTHDF1 recognizes the m6A mark on SLC7A11 mRNA to enhance the inhibition of ferroptosis, and in hepatic stellate cells, YTHDF1 also recognizes m6A mark on the BECN1 mRNA, enhancing ferritinophagy to induce ferroptosis." (PMID 37229485, 2023).
colorectal cancer (108 papers, 2010 to 2026). A primary or metastatic malignant neoplasm that affects the colon or rectum. "On the contrary, it has also been reported that BECN1 is closely linked to colorectal carcinogenesis and distant metastasis of colorectal carcinoma." (PMID 35110535, 2022). "Studies have shown that abberrant expression of Beclin-1 is strongly associated with the poor survival of various tumors such as intrahepatic cholangiocarcinoma, endometrial adenocarcinoma, colorectal cancer." (PMID 33768004, 2021). "Beclin 1 expression was inversely associated with liver metastasis and distant metastasis of colorectal cancer, or venous invasion, lymph node metastasis, TNM staging, dedifferentiation and favorable prognosis of gastric cancer." (PMID 33425768, 2020). "A series of studies have demonstrated the correlation between autophagy microtubule-associated protein light chain 3 (LC-3), Beclin-1, and colorectal cancer (CRC)." (PMID 32280357, 2020). "A recent meta-analysis showed that elevated beclin-1 expression is associated with tumor metastasis and a poor prognosis in patients with colorectal cancer." (PMID 26965179, 2016). "Our data show that p62, LC3 and Beclin-1 represent promising novel therapeutic targets especially in the subgroup of KRAS-mutated colorectal cancer patients." (PMID 27444698, 2016). "It was suggested that Beclin 1 expression is closely linked to colorectal carcinogenesis and distant metastasis of colorectal carcinoma." (PMID 25196438, 2014). "Other studies have also linked BECN1 overexpression with reduced survival in colon cancer patients treated with adjuvant 5-FU and lower BECN1 expression with a longer median progression-free survival in patients with advanced colorectal cancer treated with cetuximab-containing chemotherapy." (PMID 24723943, 2014). "CPUK02 (1,6,8,10,16,32 and 64 μM in two cell lines) treatment inhibited the UPR and modulated autophagy by decreasing Beclin-1 and increasing P62 and LC3βII mRNA levels in colorectal cancer cells." (PMID 41346768, 2026). "Tumor-derived lactate promotes the transcription of RUBCNL/Pacer through H3K18la and promotes the maturation of autophagosomes by interacting with BECN1 (beclin 1), thus promoting the resistance of colorectal cancer to bevacizumab." (PMID 40153584, 2025). "Meanwhile, IL-6 induced chemotherapeutic resistance by activating autophagy via IL-6/JAK2/BECN1 signaling pathway, as seen in colorectal cancer." (PMID 40160826, 2025). "Peng’s study explored how the interaction between ABHD5 and BECN1 regulates autophagy and affects the development of colorectal cancer." (PMID 39328203, 2024). "In colorectal cancer, IL-6 induces Beclin-1 phosphorylation at Y333 by the JAK2 kinase, which increases Beclin-1 affinity for VPS34." (PMID 38660307, 2024). "Downregulation of microRNA-409-3p promotes aggressiveness and metastasis in colorectal cancer, while its overexpression sensitizes cells to oxaliplatin by inhibiting Beclin-1-mediated autophagy." (PMID 36769265, 2023). "In colorectal cancer, IL-6 induced autophagy through the activation of BECN1 and promoted chemotherapy resistance." (PMID 37627167, 2023). "According to the literature, Beclin-1 is a gene that plays a significant role in regulating autophagy, proliferation, and apoptosis in colorectal cancer cells (HCT-116 and SW620)." (PMID 37233465, 2023). "In the present study, several new findings were observed regarding the role of nuclear Beclin 1 in colorectal cancer." (PMID 36230664, 2022). "Collectively, these results demonstrate that depletion of BECN1 suppresses colorectal cancer growth, at least in part, via elevation of RB expression." (PMID 36230664, 2022). "Silencing of BECN1 upregulated RB protein expression resulting in cell cycle G1 arrest and growth inhibition of colorectal cancer cells." (PMID 36230664, 2022).
colorectal cancer (continued). "We further examined the correlation of RB and Beclin 1 protein expression using the human colorectal cancer tissue microarrays (TMA) consisting of colorectal cancer specimens at different clinical stages." (PMID 36230664, 2022). "Ablation of BECN1 leads to elevation of RB protein expression, resulting in inhibition of cell cycle progression and retardation of colorectal cancer cell growth in vitro and in vivo." (PMID 36230664, 2022). "In this study, we show that nuclear Beclin 1, unable to induce autophagy, can modulate RB protein expression, thereby regulating cell cycle and colorectal cancer cell growth." (PMID 36230664, 2022). "First, the expression of Beclin 1 protein was negatively correlated with tumor suppressor RB protein expression in later stages of colorectal cancers." (PMID 36230664, 2022). "We next investigated the role of the Beclin 1-RB pathway in colorectal cancer growth in xenograft mouse models." (PMID 36230664, 2022). "To investigate the correlation between RB and Beclin 1, we then analyzed the correlation between Beclin 1 and RB protein expression of colorectal cancer patients in the TCGA-COADREAD dataset obtained from LinkedOmics." (PMID 36230664, 2022). "In this study, we found that elevated Beclin 1 expression correlates with reduced RB protein in advanced stages of colorectal cancer." (PMID 36230664, 2022). "The role of autophagy core-protein Beclin 1 in colorectal cancer (CRC) development remains controversial." (PMID 36230664, 2022). "In the present study, we demonstrate that IL-6 activates autophagy through the IL-6/JAK2/BECN1 pathway and promotes chemotherapy resistance in colorectal cancer (CRC)." (PMID 34131122, 2021). "Mechanistically, IL-6/JAK2 signaling-mediated phosphorylation of BECN1 at Y333 by contributes to chemotherapy resistance in colorectal cancer, and the pharmacological inhibition of autophagy leads to reestablishment of chemotherapy sensitivity." (PMID 34131122, 2021). "The initiation of autophagy induced by the IL-6/JAK2/BECN1 signaling pathway appears to be a regulatory mechanism for chemotherapy resistance in colorectal cancer." (PMID 34131122, 2021). "The concentrations of important molecules (sICAM-1, mTOR, Beclin-1, cathepsin B) involved in the pathogenesis and poor prognosis of colorectal cancer were also evaluated by ELISA." (PMID 33918514, 2021). "We further show that the level of BECN1 Y333 phosphorylation is a predictor of colorectal cancer patient outcome and that JAK2 inhibitor treatment combined with chemotherapy is more effective in inhibiting cancer cell growth." (PMID 34131122, 2021). "Knowing that bevacizumab induces autophagy, it has been reported that genetic inhibition of BECN1 improves the anticancer effects of this drug in colorectal cancer cells." (PMID 33718194, 2021). "It induces the autophagy mediators LC3-II and Beclin-1 in colorectal carcinoma cells resistant to cisplatin." (PMID 34084146, 2021). "Furowanin A (2 and 5 μM) promoted autophagy in HT-29 and SW480 colorectal cancer cells, as shown by the formation of AVOs, the increase in Beclin 1 and LC3 II, the decrease in p62 and the increase in autophagosome numbers." (PMID 32927836, 2020). "In colorectal cancer cells, Beclin 1 inhibited cell viability, migration and invasion, lamellipodia formation, and tumor growth, induced autophagy and apoptosis." (PMID 33425768, 2020). "ARG Beclin-1 is highly expressed in colorectal cancer, and Beclin-1 high expression is positively correlated with clinicopathological variables and predicts good prognosis." (PMID 32547955, 2020). "Here, we observed significantly lower expression of BECN1 in colorectal cancers (CRCs) compared with adjacent normal colon tissue, and downregulation of BECN1 was positively related to poor prognosis in CRC patients." (PMID 32358527, 2020). "Beclin 1 was considered as a dependent factor for favorable prognosis of the colorectal cancer patients." (PMID 33425768, 2020).
colorectal cancer (continued). "Clinical studies have reported that high expression of Beclin-1 in human advanced colorectal cancer tumors is negativity correlated with the survival rate of patients." (PMID 31186406, 2019). "In another study, the ring figure protein 216 (RNF216) promoted colorectal cancer cell migration by enhancing proteasomal degradation of BECN1." (PMID 31272261, 2019). "Higher Beclin-1 expression was suggested to be a positive prognostic factor for patients with colorectal cancers, oral tongue squamous cell carcinoma and natural killer T-cell lymphoma." (PMID 30849962, 2019). "Rhus coriaria L. extract, which is commonly employed in southern Europe, promotes unfolded protein response and triggered Beclin-1 independent autophagy in colorectal cancer." (PMID 30282915, 2018). "In the present study, we found that BTG1 overexpression up-regulated the expression of ATG7, ATG14 and Beclin-1 in both colorectal cancer cells." (PMID 27447746, 2017). "Collectively, our findings indicate the dual roles of aspirin on autophagy, and demonstrate a new mechanism by which Beclin 1 acetylation impairs the anticancer effect of aspirin in colorectal cancer cells." (PMID 29088823, 2017). "Our results showed that low expressions of Beclin 1 and LC3B were correlated with metastasis in colorectal cancer, suggesting Beclin 1 and LC3B contributed to the development of metastatic CRC." (PMID 28938618, 2017). "In this study, we demonstrated that aspirin induced autophagosome formation in colorectal cancer cells, but autophagic degradation was blocked through aspirin-mediated Beclin 1 acetylation." (PMID 29088823, 2017). "Our study shows that aspirin-mediated Beclin 1 acetylation impairs the anticancer effect of aspirin in colorectal cancer cells." (PMID 29088823, 2017). "When examining the ability to predict colorectal cancer metastasis through logistic regression analysis, the expression of Beclin 1, LC3B and the serum CEA level were discovered to be accurate predictive biomarkers." (PMID 28938618, 2017). "Low expression of Beclin 1 was mostly discovered in poorly differentiated colorectal cancer samples." (PMID 28938618, 2017). "From the literature search, it is found that increased protein Beclin-1 expression occurs in intrahepatic cholangiocarcinoma, colorectal cancer, and gastric cancer." (PMID 26494988, 2015). "The transfection of the low BECN1 gene-expressing colon cancer cells with the BECN1 gene inhibited cell growth, and cell cycle analysis revealed G1 arrest, indicating that BECN1 plays an important role in the proliferation of colorectal cancer cells." (PMID 24723943, 2014). "It has been shown that Beclin 1 is overexpressed in gastric cancer and colorectal cancer, which is consistent with our results." (PMID 24675697, 2014). "As for LC3 expression, the heterogeneity due to the mix of colon and rectal cancers as well as the variation in the stage from stage I to IV complicates the interpretation of the prognostic value of BECN1 expression in colorectal cancers." (PMID 24723943, 2014). "Relationship between Beclin 1 protein expression and clinicopathological features of colorectal carcinomas." (PMID 25196438, 2014). "The expression of Beclin 1 mRNA and protein was found to be higher in colorectal carcinoma than matched mucosa by real-time PCR and Western blot (p < 0.05)." (PMID 25196438, 2014). "Here, the mRNA and protein expression of Beclin 1 were determined in colorectal carcinoma and matched mucosa by Reverse transcriptase-polymerase chain reaction and Western blot." (PMID 25196438, 2014). "In contrast, overexpression of beclin-1 has been reported to correlate with progression of gastric and colorectal cancer." (PMID 23935917, 2013). "It is concluded that Beclin 1 has an important role in growth and metastasis of human colorectal cancer." (PMID 20842118, 2010).